CBX7 (chromobox 7)
Diseases named in the same sentence as CBX7 in open-access papers (continued):
Sharing a sentence is not in itself a finding about the gene and the disease.
breast carcinoma (22 papers, 2014 to 2024). "CBX2 and CBX7 as the most differentially expressed isoforms in breast tumors compared to normal and the only two members whose expression is associated with breast cancer aggressiveness highlight the biological relevance of their determined metabolic roles." (PMID 33400401, 2021). "Reduced expression levels of CBX7 have been found to be associated with a poorer OS and the aggressiveness of thyroid cancers, colorectal cancers and breast cancers, In HCC, the downregulation of CBX7 may be related to a short OS." (PMID 34046352, 2021). "Likewise, a positive correlation between loss of CBX7 expression and poor prognosis was found in human colon and breast carcinomas." (PMID 28030829, 2017). "In bladder transitional cell carcinoma, the CBX7 is another target silenced by miR-9, and it has been shown that CBX7 suppresses metastasis of basal-like breast cancer through Twist1/EphA2 pathway." (PMID 37369946, 2023). "HMGA1 can also negatively regulate CBX7, and CBX7 negatively regulates the expression of miR-181b to affect the progression of breast cancer." (PMID 35864955, 2022). "In breast cancer, CBX7 increases Dickkopf-1 (DKK-1, a Wnt antagonist) gene transcription, thus indirectly affecting the Wnt signaling pathway." (PMID 34659360, 2021). "It has been determined that the protein level of CBX7 is positively correlated with NEAT1 in breast cancer cells, proving that CBX7 is indeed a target gene regulated by NEAT1." (PMID 34659360, 2021). "Together, these results hint at the role of CBX2 and CBX7 in modulating mTORC1 pathway to promote aerobic glycolysis in breast cancer." (PMID 33400401, 2021). "Bioinformatic analysis of Chromobox proteins family has shown that the most significant difference between breast cancer and normal mammary tissue is the low mRNA expression of CBX7." (PMID 34659360, 2021). "Overall, these in vitro results were found to be consistent with the findings of the transcripto‐metabolomic analysis and validated the roles of CBX2 and CBX7 in metabolic reprogramming of breast cancer." (PMID 33400401, 2021). "It has been reported that with the down-regulation of NEAT1, the expression of CBX7 protein in breast cancer cells is also significantly down-regulated (p < 0.01)." (PMID 34659360, 2021). "We found that the most significant difference between breast cancer and normal tissues was the mRNA expression of CBX7." (PMID 33082469, 2020). "The expression difference of CBX7 was the greatest, and CBX7 was downregulated in breast cancer tissues compared with normal breast tissues." (PMID 33082469, 2020). "We found that CBX2 protein was highly expressed in the breast cancer tissues compared with normal tissues, and expression of CBX7 protein in breast cancer tissues was lower than tumor-adjacent normal tissues." (PMID 33082469, 2020). "Augmentation of CBX7 via knockdown of miR-182 expression governs cell morphology via the expression of E-cadherin in breast cancer." (PMID 31709304, 2019). "One study showed that augmentation of CBX7 by miR-182 knockdown positively regulated E-cadherin expression in human breast cancer." (PMID 31709304, 2019). "We found that breast cancer subtypes could be assigned with >90% diagnostic accuracy, as indicated by the area under the ROC curve of the partition tree, by differential expression analysis with respect to a normal breast tissue reference using only 4 genes: CBX7, ESR1, FOXC1, and FOXM1." (PMID 29868123, 2018). "Consistently, we previously demonstrated that CBX7 negatively regulates the expression of miR-181 that has among its targets CBX7, creating a synergistic loop that contributes to breast cancer progression." (PMID 28259135, 2017). "Also, CBX7 knockdown in breast cancer cells increased the frequency of cancer stem cell-like population and reinforced in vitro self-renewal and in vivo tumor-initiating ability of those cells." (PMID 36361869, 2022).
breast carcinoma (continued). "In these ways, CBX7 acts as an intermediate in breast cancer, creating a series of chain reactions." (PMID 34659360, 2021). "Furthermore, we provide evidence for the role of mammalian target of rapamycin complex 1 signaling in mediating contrary effects of CBX2 and CBX7 on breast cancer metabolism." (PMID 33400401, 2021). "CBX2 and CBX7 play oncogenic and tumor‐suppressive roles, respectively, in breast cancer." (PMID 33400401, 2021). "Therefore, CBX7 plays a cancer-inhibiting role by guiding the synthesis of DKK-1 to attenuate the Wnt pathway in breast cancer cells." (PMID 34659360, 2021). "However, CBX7 content in breast cancer is often very low, indicating that CBX7 plays its other tumor suppressor role independently of PRC1." (PMID 34659360, 2021). "The increase of glycolysis induced by silencing CBX7 may imply that CBX7 regulates the mTORC1 pathway to control aerobic glycolysis in breast cancer." (PMID 34659360, 2021). "Interestingly, both DKK-1 and sFRP4 are antagonists of the Wnt signaling pathway, but the effect of CBX7 in regulating sFRP4 in colon cancer is quite different from the effect of regulating DKK-1 in breast cancer." (PMID 34659360, 2021). "Moreover, compared with CBX7+/+MEFs(mouse embryonic fibroblasts), CBX7−/−MEFs show a higher level of miR-181 in breast cancer while CBX7 ± MEFs express a moderate level, suggesting that CBX7 negatively regulates the expression of miR-181." (PMID 34659360, 2021). "In addition, there is evidence that CBX7 also plays an important role in controlling glucose metabolism in breast cancer cells." (PMID 34659360, 2021). "The mechanism for its carcinogenicity may be that CBX7 acts as a novel epigenetic regulator of the Wnt/β-catenin pathway in breast cancer to determine cancer progression." (PMID 34659360, 2021). "Moreover, miR-181b negatively regulates CBX7 expression in breast cancer, leading to promotion of cell-cycle progression." (PMID 31709304, 2019). "Moreover, higher mRNA expressions of CBX4 and CBX7 were detected in Luminal subtypes than Basal-like subtypes of breast cancer." (PMID 29190923, 2017). "Furthermore, small hairpin RNA-mediated CBX7 knockdown in breast epithelial and breast cancer cells increased the CD44+/CD242/ESA+ cell population and reinforced self-renewal and tumor-initiating ability." (PMID 28388562, 2017). "CBX7 was 8.782-fold elevated in breast cancer samples as compared with normal tissues (p=1.83E-13)." (PMID 29190923, 2017). "The results also demonstrated that CBX7 high mRNA expression was significantly correlated to longer RFS in patients who have received adjuvant chemotherapy only (HR=0.7, p=0.023), indicating a potential role of CBX7 in contribution to chemosensitivity in breast cancer." (PMID 29190923, 2017). "Of noteworthy, the results demonstrated that CBX7 high mRNA expression was significantly correlated to longer RFS in patients who treated with tamoxifen only (HR=0.74, p=0.037), indicating a potential role of CBX7 in contribution to tamoxifen sensitivity in breast cancer." (PMID 29190923, 2017). "This could be achieved by either employing the tumor suppressive role of CBX7, as it has been proposed for breast cancer, or by controlling miR-375 levels." (PMID 27449098, 2016). "The reason why CBX7 is lost in breast cancer cells may be ascribed to lncRNA NEAT1 targeting CBX7." (PMID 34659360, 2021). "Interestingly, CBX2, which is homologous to CBX7, has a high content in breast cancer." (PMID 34659360, 2021). "Interestingly, the mechanism of increasing PTEN transcription may be the same as the enhanced DKK-1 expression in breast cancer, where CBX7 recruits p300 independently of PRC1 to the promoter region to participate in epigenetic changes." (PMID 34659360, 2021).
breast carcinoma (continued). "Considering the complex and heterogeneous nature of glycolytic regulation concerning the players and mechanism involved, unraveling the mTORC1‐mediated metabolic roles CBX2 and CBX7 may improve our understanding about how glucose metabolism is regulated in breast cancer." (PMID 33400401, 2021). "Besides, CBX6 was positively correlated with CBX7 in breast cancer." (PMID 33082469, 2020). "Using the integrative approach, we attempt here to delineate the role of aberrant CBX expression in metabolic reprogramming and identify CBX2 and CBX7 (referred as CBX2/7, hereafter) as antagonistic regulators of aerobic glycolysis in breast cancer." (PMID 33400401, 2021). "Using transcriptomic and metabolomic data from breast cancer patients (N > 3000 combined), we performed pathway‐based analysis and identified outstanding roles of CBX2 and CBX7 in positive and negative regulation of glucose metabolism, respectively." (PMID 33400401, 2021). "CBX2, CBX4, CBX6, CBX7, and CBX8 are subunits of distinct polycomb repressive 1 complexes that have important functions in the development and progression of breast cancer." (PMID 33082469, 2020). "A recent study showed that CBX7 recruited p300 acetyltransferase to the DKK1 promoter region, driving DKK1 expression in breast cancer cells and leading to the impairment of Wnt/β-catenin signaling and breast tumorigenesis." (PMID 28030829, 2017). "Moreover, in breast cancer, low expression of CBX7 may serve as prognostic marker." (PMID 27449098, 2016). "In addition, CBX7 has been found to suppress pancreatic cancer progression by inhibiting AKT signaling 25 and to inhibit tumorigenicity in breast cancer through the Wnt/β-catenin pathway." (PMID 35342353, 2022). "In breast cancer, due to the lack of CBX7, the transcriptional activation complex p300/CBP dissociates from the promoter region of DKK-1 and restarts HDAC-mediated DKK-1 gene silencing." (PMID 34659360, 2021). "However, higher mRNA expressions of CBX4 and CBX7 were detected in Luminal A and Luminal B subtypes than Basal-like and HER-2 subtypes of breast cancer." (PMID 29190923, 2017). "Also, other CBX family members like CBX3, CBX4, CBX5, CBX6, CBX7 and CBX8 express different patterns in breast cancer compared with other cancer types cells." (PMID 29190923, 2017). "Conversely, FOSL-1 and FOSL-2, whose overexpression leads to enhanced tumour cell motility and invasion in breast cancer, colorectal cancer and mesothelioma, were not regulated by CBX7 (data not shown)." (PMID 24865347, 2014). "Moreover, miR-181b induced by high mobility group AT-hook 1 (HMGA1) interferes with CBX7 mRNA at the translation level to inhibit its expression, resulting in a lack of CBX7 in breast cancer." (PMID 34659360, 2021). "Not surprisingly, like CBX7 in breast cancer, abnormal activation of the Wnt signaling pathway is found in 90% of colon cancer, and one of the reasons may be the absence of secreted frizzled-related protein 4(sFRP4)." (PMID 34659360, 2021).
glioma (20 papers, 2010 to 2025). A benign or malignant brain and spinal cord tumor that arises from glial cells (astrocytes, oligodendrocytes, ependymal cells). "In summary, our results suggest that CBX7 expression is associated with the malignancy grade of glioma and patient outcome." (PMID 28388562, 2017). "Reduced expression of the PRC1 subunit CBX7 has been implicated in bladder, breast, colon, glioma, lung, pancreatic, and thyroid carcinomas, and CBX7 knockout mice develop lung and liver carcinoma." (PMID 27588417, 2016). "Further, we observed that the exogenous overexpression of Cbx7 leads to the suppression of colony formation, induction of apoptosis as well as loss of migratory and invasive potential of glioma cells." (PMID 27291091, 2016). "We demonstrated that Cbx7 potentiation inside the glioma cells resulted in the loss of YAP/TAZ driven transcriptome as evidenced by the negative enrichment of the YAP/TAZ targets." (PMID 27291091, 2016). "In this study, we show that the invasive ability of glioma cells was decreased following CBX7 overexpression and CBX7 overexpression was associated with Wnt/β-catenin pathway inhibition, which also decreased downstream expression of ZEB1, a core epithelial-to-mesenchymal transition factor." (PMID 28388562, 2017). "Representative images show that CBX7 was primarily localized in the cytoplasm, and quantitative analysis demonstrated that CBX7 expression varied among different grades of gliomas, with lower expression in higher-grade gliomas." (PMID 39988672, 2025). "At the same time, some studies have proved that miR-18a promotes the occurrence and development of glioma by regulating the expression of CBX7, HMBOX1, and ALOXE3." (PMID 38879468, 2024). "Cbx7 acts as tumor inhibitor and is significantly downregulated in bladder, breast, liver, colon, thyroid, glioma, and pancreatic cancers." (PMID 36361869, 2022). "U251 and U87 glioma cells with gene intervention were used to validate the role of CBX7/8 in tumor proliferation and invasion." (PMID 36034290, 2022). "In line with the results of CBX7 in the glioma and pancreatic cancers, the low CBX7 expression was closely related to the poor disease prognosis of CC." (PMID 33748425, 2021). "Not only that, there is a strong connection between CBX7 and the Hippo signaling pathway in gliomas." (PMID 34659360, 2021). "CBX7 is lowly expressed in cancers of the breast, pancreas, liver, thyroid, colon, and glioma, but highly expressed in cancers of the stomach, prostate, and lymph." (PMID 34659360, 2021). "YAP is significantly upregulated in gastric dysplasia, gastric adenocarcinoma and metastatic gastric cancer, while Cbx7 inhibits the migration of glioma cells by inhibiting the YAP/TAZ‐CTGF‐JNK signalling axis." (PMID 32892482, 2020). "In general, the EMT-like process, because of little epithelial origin in glioma, was decreased following CBX7 expression, as evidenced by the expression of epithelial and mesenchymal markers in these cell lines." (PMID 28388562, 2017). "Taken together, CBX7 participates in G1/S checkpoint control and is a novel prognostic marker in glioma patients." (PMID 28460453, 2017). "Results from bioluminescence imaging showed that growth of glioma was significantly suppressed by CBX7 overexpression." (PMID 28460453, 2017). "Overall, these data show that CBX7 overexpression reduces the migration and invasion capabilities of glioma cells." (PMID 28388562, 2017). "We found that CBX7 mRNA levels in high-grade gliomas (HGG) were significantly decreased compared to normal brain tissues (NBT) and low-grade gliomas (LGG)." (PMID 28460453, 2017). "Both western blotting and immunohistochemistry assays indicated that CBX7 expression was highest in normal tissues and gradually decreased as glioma malignancy grade increased." (PMID 28388562, 2017). "We found that the expression of CBX7 in four public databases was significantly lower in high grade glioma (HGG)." (PMID 28460453, 2017).
glioma (continued). "The epithelial marker E-Cadherin is rarely expressed in gliomas and positively correlates to CBX7 expression, as previously demonstrated by ChIP assays in other cancer types." (PMID 28388562, 2017). "To investigate potential roles for CBX7 in glioma, we first studied CBX7 expression in human glioma databases." (PMID 28388562, 2017). "We observed that increased CBX7 protein levels inhibited glioma cells proliferation, migration and invasion." (PMID 28460453, 2017). "Database analysis revealed the presence of CBX7 protein in normal brain tissues and glioma tissues, but lower expression in glioma tissues." (PMID 28388562, 2017). "These multi-center data and tumor samples revealed that CBX7 is a potential prognostic factor in glioma patients." (PMID 28460453, 2017). "Based on our data, CBX7 should be added to this growing list of β-catenin regulators in glioma that includes SFRP1, DKK1 and Wif1." (PMID 28388562, 2017). "Further functional study identified that inhibition of the YAP/TAZ-CTGF-Akt signaling axis by exogenous overexpression of Cbx7 induced cell death and inhibited cell proliferation, colony formation, and migration/invasion of the glioma cells." (PMID 28415761, 2017). "Bioinformatics database-based results demonstrated that CBX7 was closely related to the progression and prognosis of gliomas and participated in cell cycle regulation." (PMID 28460453, 2017). "CBX7 expression is decreased in glioma, especially in higher grade cases, according to data in the CGGA, GSE16001 and TCGA databases." (PMID 28388562, 2017). "Then bioinformatics analysis indicated that CBX7 played a tumor suppressor role in glioma progression, especially in cell cycle control." (PMID 28460453, 2017). "The result showed that there was a significant inverse correlation between CBX7 level and glioma grade." (PMID 28460453, 2017). "In consideration of these data, we further investigated the role of CBX7 in glioma on migration and invasion especially." (PMID 28388562, 2017). "We observed that decreased CBX7 protein levels enhanced glioma cells proliferation, migration and invasion." (PMID 28460453, 2017). "Although it was reported that CBX7 was downregulated and inhibited cell migration in glioma cells, the effect of CBX7 on cell cycle disregulation, another typical characteristic of GBM, is still unclear." (PMID 28460453, 2017). "In conclusion, our in vitro and in vivo results validate the assumption that CBX7 is a tumor suppressor of gliomas." (PMID 28460453, 2017). "CBX7 overexpression decreases Wnt/β-catenin signaling and blocks glioma cell invasion mediated by DKK1, which was verified in LN229, T98G and PGC cell lines." (PMID 28388562, 2017). "Considering the contradictory role of CBX7 in different tumors, the transcription level of CBX7 in four glioma databases (CGGA, TCGA, REMBRANDT and GSE16011) was analyzed." (PMID 28460453, 2017). "Further experimental evidence has shown that exogenous CBX7 overexpression induced apoptosis and inhibited cell proliferation, colony formation and migration of glioma cells." (PMID 28388562, 2017). "Non-invasive bioluminescence imaging and survival times of nude mice revealed that CBX7 behaved as a tumor suppressor gene in gliomas." (PMID 28460453, 2017). "We found that the exogenous overexpression of CTGF significantly rescued the migratory potential of the Cbx7 stable glioma cells (compare 3 and 4)." (PMID 27291091, 2016). "To dissect the signalling pathway downstream of CTGF responsible for Cbx7 mediated inhibition of glioma cell migration, we analysed the phosphorylation status of various kinases in Cbx7 overexpressing cells." (PMID 27291091, 2016). "All together, we conclude from these results that Cbx7 inhibits glioma cell migration by inhibiting YAP/TAZ-dependant activation of CTGF with the resultant reduced signalling by phospho-SAPK/JNK." (PMID 27291091, 2016).